CD4 (CD4 molecule)
Diseases named in the same sentence as CD4 in open-access papers (continued):
Sharing a sentence is not in itself a finding about the gene and the disease.
diabetes (677 papers, 2006 to 2026). "Our observations also align with earlier Tanzanian research, which found that lower CD4 counts and high BMI are associated with an increased risk of diabetes." (PMID 41399597, 2025). "Hypertension, dyslipidemia, CVDs, diabetes, and recent low CD4+ cell count have all been associated with the risk of CKD in PLWH." (PMID 41585876, 2025). "The heightened risk is mainly due to HIV-induced renal injury, diminished CD4+ counts, treatment-related effects, and the presence of comorbidities such as diabetes and hypertension." (PMID 39056083, 2024). "NOD mouse B cells genetically modified to be MHC class I or II deficient (to prevent antigen presentation to CD8+ or CD4+ T cells) prevented diabetes." (PMID 38515750, 2024). "By contrast, other studies reported that PD-1 deficient CD4+ Tregs were more functional as inhibiting efficiently experimental autoimmune encephalomyelitis or diabetes in mice." (PMID 38512889, 2024). "The prevalence of renal dysfunction induced by TDF is estimated at 5.6%, and the risk is increased with advanced age, low BMI, low baseline CD4 count, hypertension, and diabetes." (PMID 38799537, 2024). "We found that splenocytes from vaccinated mice that were rendered deficient in CD4 cells promoted diabetes much less than similar cell from vehicle-treated mice." (PMID 38543910, 2024). "For example, with adjustment for diabetes risk factors, the relative risk estimate was 0.93 (95% CI: 0.84, 1.04; p = .16) per 1‐SD higher proportion of CD4+ naive cells and 1.09 (95% CI: 0.97, 1.23; p = .16) per 1‐SD higher value of CD4+ memory cells." (PMID 36333945, 2023). "The results of multivariable logistic regression analysis indicated uncontrolled diabetes, platelets < 40 × 109/L, CD4+ T cell < 300/μL, and CD8+ T cell < 400/μL were associated with occurrence of IPA in SFTS patients." (PMID 36707667, 2023). "Many HIV-related variables were linked with the development of diabetes, including a reduced CD4 T-cell nadir and a decreased CD4 cell count at the beginning of ART, for which data on viral load was available for a subset of the population (N = 1065)." (PMID 37746464, 2023). "Results of univariate analysis showed that uncontrolled diabetes, central nervous system symptoms, platelet < 40 × 109/L, CD4+ T cell < 300/μL and CD8+ T cell < 400/μL were risk factors for development of IPA." (PMID 36707667, 2023). "Increasing age, male gender, overweight or obesity, co-morbid diabetes mellitus or renal disease, and CD4 count ≥ 201 cells/μL were significantly associated with prevalent hypertension." (PMID 37908015, 2023). "On metaregression for age, baseline CD4, and viral load, we found a pattern of an increased risk of diabetes with higher baseline viral loads and low CD4 cell counts." (PMID 36754450, 2023). "In the general population, a reduced proportion of naïve and regulatory (Treg) CD4+ T cells, higher circulating memory CD4+ T cells, and a shift towards pro-inflammatory Th1 and Th17 helper cells was associated with prevalent diabetes." (PMID 37313404, 2023). "Both EBV-infected B cells and EBV antigen-specific CD4 CTLs that are cross-reactive with diabetes-associated antigens would infiltrate pancreatic islets." (PMID 35894054, 2022). "West African ancestry and demographic factors were no longer associated with ESKD after adjustment for APOL1 status, whereas low CD4 cell count, diabetes, and cardiovascular disease remained associated with ESKD." (PMID 35497797, 2022). "Using the nomogram, we developed individualized PD risk prediction models including CD8+ Tn cells, LD CD4+ T cells, and independent risk factors such as the status of diabetes mellitus, smoking, alcohol consumption, and tea consumption." (PMID 35608657, 2022). "Kebede56 found, using a multilevel analysis, that among the parameters evaluated, the hemoglobin level and weight of patients were linked with the CD4 count of patients with diabetes." (PMID 36477157, 2022).
diabetes (continued). "Nonobese diabetic (NOD) mice that lack CD28 signaling are deficient in CD4+ Tregs which results in exacerbated onset of spontaneous diabetes." (PMID 36761170, 2022). "The decreased number of CD3+CD4+ T cells and increased level of IL-6 were independent risk factors of cardiac injury, which can be promoted by the presence of diabetes." (PMID 36123740, 2022). "We then looked at regulatory T cells, because other laboratories previously reported an increase in CD4+ CD25+ FoxP3+ “Tregs” in NOD mice as diabetes developed." (PMID 36291615, 2022). "In line with the in vitro coculture results, the Tlr7-deficient B cells significantly delayed the diabetes development induced by diabetogenic CD4+ T cells in the Rag−/− NOD recipients." (PMID 33432061, 2021). "T cell-specific transgenic NOD mice overexpressing SUMOylation site-mutated c-Maf developed diabetes more rapidly than Tg-WTc mice in a CD4+ T cell-intrinsic manner." (PMID 34336833, 2021). "Low CD4 count has previously been associated with diabetes in HIV-infected individuals and helps explain the links between infectious and non-communicable diseases." (PMID 32267855, 2020). "In our analysis, ageing, being male, and CD4 counts <200 cells/μL were significantly associated with diabetes by one or both tests." (PMID 32267855, 2020). "For both OGTT and HbA1c tests, similar other risk factors, e.g. low CD4 count and low physical activity, were associated with increased risk of diabetes." (PMID 32267855, 2020). "One had HIV with low CD4 count and another patient had diabetes as possible causes for immunosuppression for both infections." (PMID 32669124, 2020). "CD4 count < 200 cell/μL at recruitment increased risk and physical activity decreased risk of diabetes by both HbA1c and OGTT." (PMID 32267855, 2020). "In a univariate analysis, older age, male gender, a family history of hypertension, duration of HIV infection, duration on ART, high body mass index, low CD4 count, diabetes, and renal impairment were associated with hypertension." (PMID 31929895, 2019). "We confirmed previous findings that IFNγR-deficiency causes resistance to CD4+ T cell-mediated diabetes." (PMID 30555479, 2018). "In the univariate analysis of factors associated with health care delay, being black/brown, having diabetes, having higher CD4 counts and having previous diagnosis of HIV were associated with greater risk of greater health care delay." (PMID 29624603, 2018). "In this system, transfer of CD4+ T cells isolated from NOD-Idd9/11NOR mice caused less diabetes than CD4+ T cells isolated from NOD." (PMID 29527189, 2018). "Independent predictors associated with increased peritonitis risk were HIV (HR, 1.84; CI, 1.07–3.16; P = 0.027), diabetes (HR, 2.09; CI, 1.09–4.03; P = 0.027) and a baseline CD4 count < 200 cells/μL (HR, 3.28; CI, 1.42–7.61; P = 0.006)." (PMID 28158991, 2017). "Data utilizing NOD mice congenic for the diabetes-resistant alleles at the Idd3 and Idd5 loci demonstrated that expression of these alleles is important in DCs for CD4+ T and CD8+ T cell tolerance." (PMID 26124756, 2015). "Risk factors for renal dysfunction included age ≥45 years, diagnosed diabetes, underlying renal disease, underweight and CD4 count <200cells/mm3." (PMID 26301416, 2015). "In the adjusted analysis, female gender, age ≥45 years, diabetes, renal disease, under-nutrition, CD4 count <200cells/mm3were associated with developing renal dysfunction." (PMID 26301416, 2015). "We found that baseline factors such as age≥45 years, being female, underweight, having underlying renal disease and diabetes, and low CD4 count were associated with the development of renal dysfunction." (PMID 26301416, 2015). "Co-morbidities (hepatitis C, diabetes), low body weight, older age, concomitant administration of potentially nephrotoxic drugs, low CD4 count, and duration of therapy are all risk factors associated with tubular dysfunction." (PMID 25426075, 2014).
diabetes (continued). "Co-morbidities (hepatitis C, diabetes), low body weight, older age, concomitant administration of potentially nephrotoxic drugs, low CD4 count, and duration of therapy are all risk factors associated with tenofovir-associated tubular dysfunction." (PMID 25426075, 2014). "The small sample size in the CD4 ≤200 cells/μl stratum and the diabetes group resulted in limited power to detect associations." (PMID 24236170, 2013). "The logistic analysis showed that older age, lower CD4 count and minority ethnicity were significantly associated with an increased risk of diabetes." (PMID 23394285, 2013). "Older age, lower CD4 count and minority ethnicity were significantly associated with an increased risk of diabetes." (PMID 23394285, 2013). "● Associations were found between diabetes mellitus, arterial hypertension, CD4+ T cell count, and CHD." (PMID 23230442, 2012). "Adoptive transfer of CD4+ T cells to T-cell-deficient Rag1−/− mice reduced obesity and improved diabetes." (PMID 23027613, 2012). "Logistic regression analysis showed significant associations (p < 0.05) between traditional risk factors such as diabetes mellitus, hypertension, and CD4+ T cell count at HIV-infected diagnosis and CHD." (PMID 23230442, 2012). "Viral factors which contribute to diabetes risk are an increase in viral burden of 0.5 log over a 6 month period, a lower CD4 count, and longer duration of HIV infection." (PMID 21232158, 2011). "Similarly, CD4+ T cell clones specific for InsB9-23 can cause diabetes in adoptive transfer models in lymphopenic mice." (PMID 41596443, 2026). "As the prevalence of CKD is often associated with hypertension, diabetes, age, obesity, and low CD4+ counts in PLWH, it is also essential to determine whether these risk factors are associated with the presence of CKD among PLWH in South Africa." (PMID 39056083, 2024). "The utility of this measurement is demonstrated by our patient with a novel missense variant in the alternatively spliced exon two who had isolated diabetes at age 5 years but in whom the TSDR/CD4 value was raised leading to reclassification of the variant as likely pathogenic." (PMID 36600150, 2023). "Identifying increased %TSDR/CD4 in patients with novel FOXP3 mutations presenting with isolated diabetes facilitates diagnosis and could offer an opportunity to monitor patients and begin immune modulatory treatment before onset of severe enteropathy." (PMID 36600150, 2023). "Finally, we tested the regulatory function of these engineered B cells in vivo for their capacity to protect NOD.Scid mice from diabetes development by adoptively transferring pathogenic antigen-specific CD8+ or CD4+ T cells into NOD.Scid hosts." (PMID 37731505, 2023). "CD4 count and diabetes as independent factors influencing the diagnostic accuracy of LAM." (PMID 38145052, 2023). "Several risk factors have been associated with postoperative SIRS including mannose-binding lectin deficiency, high levels of circulating GM-CSF + CD4+ T cells, bacteriuria and renal stone size, diabetes mellitus, and the intraoperative use of an intra-aortic balloon pump." (PMID 37139371, 2023). "Interestingly, it was the phenotypes that correlated with biological age, namely CD4 Tn/Tm and CD4 Tn, that were also associated with multimorbidity, cancer, diabetes and heart disease." (PMID 37116193, 2023). "Together, these data suggest that the promotion of diabetes progress by plasmablasts may be associated with the enhanced activation and proinflammatory response of CD4+ T cells." (PMID 35123388, 2022). "Sepsis patients with diabetes mellitus in the observation group were associated with the lowest CD4+ and CD8+ levels in the control group, followed by the sepsis patients in the experimental group, and then the healthy participants in the control group (P < 0.05)." (PMID 35664433, 2022).
diabetes (continued). "Since cancer was the third most frequent chronic condition (after heart disease and diabetes), this may reflect the strong association between cancer and CD4 + T cells." (PMID 35858901, 2022). "Interestingly, our patients had underlying diseases, such as CF, HIV with a low CD4 count, diabetes, and renal disease." (PMID 35606506, 2022). "According to our results, those individuals with a nadir CD4+ T-cell count < 350 cells/mm3, lower education level and the presence of comorbidities such as diabetes mellitus had an increased risk of developing NI and should be prioritized in neurocognitive assessment among HIV older adults." (PMID 35109939, 2022). "Since the CD4 + TN/TM and CD4 + TN CD4 subsets were associated with the three most common chronic conditions (heart disease, diabetes and cancer), this could explain the significant association between these subsests and multimorbidity score of two." (PMID 35858901, 2022). "Interestingly, a variant m.3394T>C in ND1 risky for short-term CD4+T-cell recovery which was found in our regression analyses contributes to the development of East-Asian metabolic syndrome and type 2 diabetes mellitus." (PMID 34970271, 2021). "Moreover, the pathogenicity of CD4+ T cells was much increased, and this significantly accelerated the development of diabetes when these CD4+ T cells were transferred into immune-deficient NOD mice." (PMID 34394099, 2021). "To further test if Tlr7-deficient B cells attenuate diabetes development, we adoptively transferred Tlr7-deficient or Tlr7-sufficient B cells together with purified CD4+ T cells (Tlr7 sufficient) from diabetic NOD mice into immunodeficient Rag−/− NOD recipients." (PMID 33432061, 2021). "The association of CD4 count with diabetes suggests that immune impairment resulting from HIV infection may magnify the risk of glucose dysregulation." (PMID 32267855, 2020). "Similarly, in mice, transfer of ZnT8 C-terminal-specific CD4+ T cells only caused diabetes if insulitis was present." (PMID 31444530, 2019). "PAD is associated with older age, diabetes, smoking and low CD4 cell counts." (PMID 31026289, 2019). "The findings observed in our study with FDR of T2DM subjects and other studies with T1DM patients and their FDR may suggest that the imbalance in the CD4/CD8 lymphocyte ratio might be figured among factors associated with diabetes development." (PMID 30983877, 2019). "Nonobese diabetic (NOD) mice, a widely used model of human disease that spontaneously develop diabetes, are protected from the disease onset when deficient in CD4 T cells, and enriched CD4+ cells from diabetic donors are able to transfer the disease when administered into NOD-scid/scid recipients." (PMID 30061883, 2018). "In addition to low nadir CD4 count, older age, diabetes, hypertension, and COPD were all associated with elevated odds of AF/AFL among HIV+ persons." (PMID 29558525, 2018). "Guidelines for the management of HIV-positive patients recommend annual screening by urinalysis for proteinuria and eGFR or creatinine clearance for high-risk patients (persons of African descent, CD4 <200, diabetes, hypertension, or HCV) and prior to the initiation of ART." (PMID 26317657, 2015). "Subsequently, the cytokines and activated immune cells, especially CD8+ and CD4+T cells, attack the pancreases, leading to the chronic destruction of the islet structures, damaged β cells, autoantibody onset and diabetes progression in the SENP1-deficient mice." (PMID 26596471, 2015). "The progression of diabetes in NOD mice is mostly caused by IFN-γ+ CD4+ T (Th1) cells." (PMID 25522369, 2014). "Older age, lower CD4 count and minority ethnicity are associated with increased risk of diabetes." (PMID 23394285, 2013).
diabetes (continued). "At each visit, we determined CD4+CD25+Foxp3+ T-cell frequencies, IFN-γ cytokine production by autoreactive CD4+ T-cells in response to diabetes-associated islet epitopes, and frequencies of autoreactive CD8+ T-cells against HLA-A2-restricted antigenic epitopes." (PMID 24223938, 2013). "Since expression of CD62L is critical for leukocyte trafficking into secondary lymphoid organs, the diabetes-permissive STD diet may be associated with lower proportion of naïve CD4+ T cells migrating to mucosal compartments such as PP or the PLN." (PMID 22428018, 2012). "However, traditional risk factors such as diabetes mellitus, hypertension, and CD4+ T cell count showed association (p < 0.05) with CHD." (PMID 23230442, 2012). "Furthermore, our data suggested that increases in IRF4 expression and CD4+CD8α−CD11c+IRF4+ DCs population in NOD mice were associated with the abnormal function of DCs in diabetes-prone NOD mice." (PMID 21647406, 2011). "Finally, prevention of diabetes by injection of IL-10 expressing vector into NOD mice is associated with an increase in CD4+CD25+ regulatory T cells." (PMID 21716731, 2011). "These include age, diabetes mellitus, renal disease, history of catheter-associated infection, hypertension, dialysis duration, catheter site, catheter duration, number of catheterizations, catheter type, CD4+ cell, ALB, CRP, Hb, PCT, inadequate hand hygiene, and APACHE II scores." (PMID 38536779, 2024). "Persistent inflammation and suboptimal CD4 T-cell recovery despite virologic suppression has been implicated as causes of cognitive dysfunction, cardiovascular disease, pulmonary and renal disease, diabetes, cancer, depression, and frailty for individuals with HIV." (PMID 34449812, 2021). "However, BDC2.5+ CD4+ T cells from the BDC2.5+ NOD mouse could rapidly transfer diabetes into severe combined immune-deficient NOD (NOD.scid) recipients after activation in vitro." (PMID 34394099, 2021). "Indeed, ACs (apoptotic beta-cell infusion) could suppress beta-cell antigen-specific CD4+ T cell proliferation and delay the onset of diabetes in the diabetes-susceptible, autoimmune (NOD) mice." (PMID 31214024, 2019). "The increased colonization rate in HIV-infected women with high CD4 cell count might be biased by the presence of other risk factors for GBS colonization like diabetes or obesity, which are expected to be found more often in women with higher CD4 cell counts and were not taken into account." (PMID 27899925, 2016). "The fact that immune dysregulation associated with diabetes or alcohol misuse is a significant risk factor for melioidosis—yet more explicit disruption of CD4 immunity such as HIV infection appears less important—has supported a notion that host defense may be largely innate." (PMID 25862821, 2015). "The earliest of these isolated T cells was a CD4+ T cell clone named BDC2.5, the first of a series of BDC clones contributing to the study of pathogenic CD4+ T cells in diabetes in the NOD mouse." (PMID 41206392, 2026). "Double negative T regs have also been shown to protect the NOD mouse from diabetes in adoptive transfer studies more than CD4 + Tregs." (PMID 40106422, 2025). "Significant variables (p < 0.05): age, employment status, family history of diabetes, and CD4 <200 cells/μL." (PMID 41399597, 2025). "Within islet immune infiltrates, we demonstrated antigen-specific multifunctional IL-21+IFN-γ+CD4+ Tfh cells that were enriched in ICI-treated mice with diabetes." (PMID 40626363, 2025). "In diabetes, abnormally activated CD4+ T cells increase the expression of peripheral blood inflammatory factors by secreting the cytokines interleukin-17 (IL-17) and interferon-γ (IFN-γ)." (PMID 39630234, 2025). "Although ART markedly improves survival and immune recovery, diabetes mellitus was observed in 3.7% of this clinic cohort, with higher absolute counts among older adults and those with lower CD4 levels." (PMID 41399597, 2025).